KRTAP5-9 (keratin associated protein 5-9)
Description:
In the hair cortex, hair keratin intermediate filaments are embedded in an interfilamentous matrix, consisting of hair keratin-associated protein (KRTAP), which are essential for the formation of a rigid and resistant hair shaft through their extensive disulfide bond cross-linking with abundant cysteine residues of hair keratins. The matrix proteins include the high-sulfur and high-glycine-tyrosine keratins.
Synonyms: KRN1; KRTAP5.9; KRTAP5-1
Tractability: No criterion of Open Targets' tractability assessment is met for any kind of drug.
Gene: Protein-coding gene on chromosome 11 (71,548,420 to 71,549,608, forward strand). Ensembl gene ENSG00000254997.
Pathways (Reactome):
Developmental Biology: Keratinization
Gene Ontology:
Molecular function: identical protein binding; protein binding
Biological process: epidermis development
Cellular component: cytosol
Genetic constraint (gnomAD): Loss-of-function variants: 3 observed, 4.2 expected, observed/expected ratio (o/e) 0.71, 90% interval 0.32 to 1.67. That is too few expected variants to judge how well the gene tolerates losing a copy. Missense variants: 183 observed, 212.55 expected, observed/expected ratio (o/e) 0.86, 90% interval 0.76 to 0.97. Synonymous variants: 70 observed, 83.95 expected, observed/expected ratio (o/e) 0.83, 90% interval 0.69 to 1.02.
Homologues: Orthologues: chimpanzee KRTAP5-9 (95% identical).